KRT2 (keratin 2)
Description:
Structural component of intermediate filaments in suprabasal keratinocytes of stratified epidermis. Forms heteropolymers with type I keratins (e.g., KRT10), assembling into keratin intermediate filament networks that support mechanical integrity and resilience of the differentiating epidermis. Contributes to terminal differentiation and cornification of keratinocytes and plays a role in establishing the epidermal barrier.
Synonyms: CK-2e; K2e; KRT2A; KRT2E; KRTE
Tractability: Antibody: its Gene Ontology location is reachable by antibodies, with high confidence. PROTAC: ubiquitination databases record sites on it; its protein half-life has been measured.
Gene: Protein-coding gene on chromosome 12 (52,644,558 to 52,652,211, reverse strand). Ensembl gene ENSG00000172867.
Subcellular location: Cytoplasm
Subcellular location (Human Protein Atlas): Cytosol; Intermediate filaments
Pathways (Reactome):
Developmental Biology: Formation of the cornified envelope; Keratinization
Gene Ontology:
Molecular function: protein binding; structural constituent of skin epidermis; structural constituent of cytoskeleton; cytoskeletal protein binding
Biological process: cornification; keratinization; keratinocyte activation; keratinocyte migration; keratinocyte proliferation; epidermis development; intermediate filament organization; positive regulation of epidermis development
Cellular component: cornified envelope; cytoplasm; extracellular exosome; extracellular region; membrane; nucleus; cytosol; intermediate filament; keratin filament
Genetic constraint (gnomAD): Loss-of-function variants: 35 observed, 46.41 expected, observed/expected ratio (o/e) 0.75, 90% interval 0.57 to 1. The upper end of that interval is the gene's LOEUF score, 1, which puts it in group 4 of 6, group 1 being the genes least tolerant of losing a copy. Missense variants: 852 observed, 824.73 expected, observed/expected ratio (o/e) 1.03, 90% interval 0.98 to 1.09. Synonymous variants: 319 observed, 318.32 expected, observed/expected ratio (o/e) 1, 90% interval 0.91 to 1.1.
Homologues: Orthologues: chimpanzee KRT2 (99% identical), macaque KRT2 (94% identical), mouse Krt2 (78% identical), pig KRT2 (77% identical), rat Krt2 (77% identical), rabbit KRT2 (74% identical), guinea pig KRT2 (72% identical). Paralogues in human: KRT1 (65% identical), KRT76 (59% identical), KRT3 (59% identical), KRT5 (56% identical), KRT6C (55% identical), KRT6A (55% identical), KRT6B (55% identical), KRT77 (53% identical), KRT75 (51% identical), KRT4 (50% identical), KRT79 (49% identical), KRT73 (48% identical), and 56 more.
Diseases named in the same sentence as KRT2 in open-access papers:
KRT2 is named in the same sentence as 28 diseases in open-access papers, as found by Europe PMC text mining. Sharing a sentence is not in itself a finding about the gene and the disease. The quoted sentences say what the papers report.
epidermolytic ichthyosis (5 papers, 2020 to 2026). A rare keratinopathic ichthyosis (KPI), that is characterized by a blistering phenotype at birth which progressively becomes hyperkeratotic. "KRT2 is a kind of epidermal cytoskeletal protein, and mutations in this gene are associated with bullous congenital ichthyosiform erythroderma." (PMID 39619568, 2024). "The histologic reaction pattern of epidermolytic hyperkeratosis is also found in superficial epidermolytic ichthyosis with a keratin 2 mutation (ichthyosis bullosa Siemens), or epidermal nevi in the setting of mosaicism of keratinopathic ichthyoses." (PMID 34066992, 2021).
superficial epidermolytic ichthyosis (5 papers, 2020 to 2026). Superficial epidermolytic ichthyosis (SEI) is a rare keratinopathic ichthyosis (KI) characterized by the presence of superficial blisters and erosions at birth. "Mutations in KRT2 result in a more superficial epidermal blistering pattern, termed superficial epidermolytic ichthyosis (SEI), recognized as the second major type of KPI." (PMID 40741111, 2025). "Superficial epidermolytic ichthyosis (SEI) is an autosomal dominant inherited skin disease caused by mutations in the keratin 2 gene (KRT2)." (PMID 35887135, 2022).
ichthyoses (2 papers, 2020 to 2022). "No other potentially pathogenic mutations were identified in KRT2, nor in any other gene associated with congenital ichthyoses." (PMID 35887135, 2022).
melanoma (2 papers, 2020 to 2021). A malignant, usually aggressive tumor composed of atypical, neoplastic melanocytes. "In our report, the expression of KRT2 in primary melanoma tissues was higher than that in metastatic tissues." (PMID 33441834, 2021). "Although there was no report of KRT2 and SPRR2F as a prognostic molecule of tumors, KRT2 and SPRR2F might function as promising biomarkers in melanoma." (PMID 33133157, 2020).
periodontitis (2 papers, 2016 to 2025). An acute or chronic inflammatory process that affects the tissues that surround and support the teeth. "Genes related to keratinocyte differentiation and the epidermal differentiation complex, including keratin family members (KRT1, KRT2, and KRT10) and loricrin (LOR), were also among the most downregulated genes in periodontitis." (PMID 41124422, 2025).
psoriasis (2 papers, 2022 to 2023). An autoimmune condition characterized by red, well-delineated plaques with silvery scales that are usually on the extensor surfaces and scalp. "Importantly, the downregulation of Krt2/15 and upregulation of Krt6/16/17 have been associated with inflammation and the proliferative stage of keratinocyte differentiation under pathological conditions such as psoriasis." (PMID 37809094, 2023). "There was a positive association between the Psoriasis Area and Severity Index (PASI) score and three proteins (TFRC, IMPDH2, KRT2)." (PMID 36483564, 2022).
adenoma (1 paper, 2024). A neoplasm arising from the epithelium. "In addition to our proposed markers, KRT1, KRT2, and KRT10 were enriched in the C group among the stromal CDX2- population in our previous DVP experiment, consistent with the intensity increase observed in our larger adenoma cohort." (PMID 39252972, 2024).
epidermal nevus (1 paper, 2020). "Importantly, NGS identified for the first time a somatic KRT2 mutation, p.Asn186Asp, in a patient presenting with an extensive epidermal nevus." (PMID 33081034, 2020).
epidermolytic nevus (1 paper, 2020). "Overall, our findings expand the phenotypic and molecular spectrum of KI and show for the first time that epidermolytic nevus can be due to somatic KRT2 mutation." (PMID 33081034, 2020). "Of note, molecular genetic testing in a third case of extensive epidermolytic nevus revealed a somatic missense mutation (p.Asn186Asp) in the KRT2 gene, detected in DNA from lesional skin at an allelic frequency of 25% and, at very low frequency (1.5%), also in blood." (PMID 33081034, 2020).
Erythema (1 paper, 2023). Redness of the skin, caused by hyperemia of the capillaries in the lower layers of the skin. "Various skin abnormalities, such as hyperkeratosis, abnormality of the plantar skin of the foot, palmoplantar keratoderma, subcutaneous nodules and erythema, were associated with GJA1, KRT1, KRT2, PSEN1 and INSR." (PMID 37185447, 2023).
erythroderma (1 paper, 2022). "SEI is caused by mutations in KRT2 and frequently shows erythroderma and widespread blistering at birth." (PMID 35887135, 2022). "Erythroderma was observed in 11.1% of the cases with p.Glu487Lys in KRT2." (PMID 35887135, 2022). "Thus, we performed deep phenotyping for the age of onset and the presence/absence of erythroderma in the reported SEI cases with the identical KRT2 mutation p.Glu487Lys." (PMID 35887135, 2022). "Generally, the number of cases with erythroderma in SEI is small and it was confirmed that the majority of patients with the recurrent KRT2 mutation p.Glu487Lys never showed erythroderma." (PMID 35887135, 2022).
gastric cancer (1 paper, 2024). A primary or metastatic malignant neoplasm involving the stomach. "In our analysis of human-derived proteins in tongue coating, we observed a significant downregulation of KRT2, KRT9, and DCD in the tongue coating of gastric cancer patients." (PMID 38191439, 2024). "A total of 5 proteins, including KRT2, KRT9, DCD, EWSR1, and CACNA1G, were downregulated in gastric cancer patients in both cohorts." (PMID 38191439, 2024). "Downregulation of KRT2, KRT9, and DCD collectively indicates a decreased microbial resistance in the oral cavity of gastric cancer patients." (PMID 38191439, 2024). "Notably, we observed the downregulation of keratins KRT2 and KRT9 on the tongue surface, as well as the ABC transporter COG1136 in microbiota, in gastric cancer patients, suggesting a decrease in lingual mucosa defense ability." (PMID 38191439, 2024). "Notably, we observed the downregulation of human keratins KRT2 and KRT9 on the tongue surface, as well as the downregulation of ABC transporter COG1136 in microbiota, in gastric cancer patients." (PMID 38191439, 2024).
keratinization disorders (1 paper, 2020). "Keratinopathic ichthyoses (KI) are a clinically heterogeneous group of keratinization disorders due to mutations in KRT1, KTR10, or KRT2 genes encoding keratins of suprabasal epidermis." (PMID 33081034, 2020).
neuropathy (1 paper, 2022). A disorder affecting the nervous system that manifests with pain, tingling, numbness, and/or muscle weakness. "Notably, keratin 2 (KRT2) and KRT9 were identified at the intersection of three gene lists, which were subgroups of the keratin family related to cell structure and integrity and might be relevant to the disease progression of viral infection-induced neuropathy." (PMID 36277496, 2022).
infection (2 papers, 2017 to 2024). The state of being infected such as from the introduction of a foreign agent such as serum, vaccine, antigenic substance or organism. "In the present study KRT1 was under-expressed after chronic wound in a similar fashion than KRT2 was under-expressed in skin mucus after infection." (PMID 29197330, 2017). "Furthermore, proteins related to the cytoskeleton and cytoskeleton remodeling (KRT2 and PLXNA4) and genes coding for components of the cytoskeleton, KRT13 (LOC100515166), KRT17 (LOC100737113), KRT6A, and BFSP1, were significantly higher expressed after infection with swH1N1 compared to huH1N1." (PMID 39247193, 2024).
tumor (2 papers, 2021 to 2025). "Proteomic analysis of serum samples from PDAC patients with well‐characterized tumor subtypes revealed that several keratins, including KRT2, KRT5, KRT10, and KRT77, were highly abundant in samples from patients with basal‐like tumors." (PMID 39478658, 2025). "We also demonstrated that KRT2 expression was significantly correlated with tumor stage in patients with SKCM." (PMID 33441834, 2021).
cancer (1 paper, 2023). A tumor composed of atypical neoplastic, often pleomorphic cells that invade other tissues. "Cancer line analysis indicated significant downregulation of five cytoskeleton proteins, keratins (KRT2, KRT9, KRT1, KRT10)." (PMID 37377864, 2023).
KRT2 also shares sentences with these, for which no sentence is quoted: diabetic foot ulcer (2 papers); keratinopathic ichthyosis (2); atopic dermatitis (1); diabetic retinopathy (1); Hyperkeratosis (1); metastatic melanoma (1); oral mucosal ulcers (1); Palmoplantar keratoderma (1); thymoma (1); ulcer (1); viral infection (1).